FBXO45 (F-box protein 45)
Diseases named in the same sentence as FBXO45 in open-access papers (continued):
Sharing a sentence is not in itself a finding about the gene and the disease.
ovarian carcinoma (1 paper, 2025). A malignant neoplasm originating from the surface ovarian epithelium. "Meanwhile, we found that the high expression of FBXO45 in ovarian cancer tissues was accompanied by a corresponding elevation of WNT1 protein in clinical samples of 3 ovarian cancer tissues and normal ovarian tissues." (PMID 40990020, 2025). "As a core gene in the prognostic model, FBXO45 has the potential to function as a therapeutic target for ovarian cancer." (PMID 40990020, 2025). "FBXO45 is a key E3 ubiquitin ligase in ovarian cancer, promoting growth, spread and migration via the Wnt/β-catenin pathway." (PMID 40990020, 2025).
pancreatic ductal adenocarcinoma (1 paper, 2024). An infiltrating adenocarcinoma that arises from the epithelial cells of the pancreas. "FBXO45 expression was high and associated with poor prognosis in pancreatic ductal adenocarcinoma (PDAC)." (PMID 38773471, 2024).
pemphigus (1 paper, 2025). Pemphigus is a group of rare autoimmune diseases that cause blistering of the skin and mucous membranes (mouth, nose, throat, eyes, and genitals).This conditioncan occur at any age, but often strikes people in middle or older age. "Differential expression analysis was conducted to investigate the expression patterns of the five genes (XBP1, FBXO45, SAT2, AIFM1, and ACSL4) and eight other DEGs associated with ferroptosis (G3BP1, WBP11, TET2, IRF8, FASN, GDPD5, H1-4, and HUWE1) in both the pemphigus and control groups." (PMID 40612574, 2025).
serous ovarian cancer (1 paper, 2025). "FBXO45 was highly expressed in plasmacytoid ovarian cancer in the GSE36668 dataset of the GEO database by analyzing data from four normal ovaries and four patients with serous ovarian cancer." (PMID 40990020, 2025).
viral infection (1 paper, 2022). "The F-box protein is induced after viral infection and in an unbiased screen, FBXO45 binds IFNLR1 that appears to be localized to a region spanning 50 AA within the cytoplasmic domain." (PMID 36379255, 2022).
tumor (18 papers, 2015 to 2025). "First, our outcomes exhibited that the TWIST1 and FBXO45 expression levels were negatively associated in TNBC tumour tissues, and FBXO45 regulated TWIST1 expression in TNBC cells." (PMID 35802537, 2022). "The methylation levels of FBXO1, FBXO20, FBXO32, and FBXO45 were associated with tumor differentiation." (PMID 35046938, 2021). "In addition, FBXO45 has been shown to be associated with the progression of various tumours." (PMID 35802537, 2022). "These core genes—TRAF4, UBE2L3, FBXO45, UBE2L6, FBXL14, SKP2, CHAF1B, and WDR77—have been implicated in tumor progression in previous studies." (PMID 40990020, 2025). "To subsequently investigate the functional impact of FBXO45 knockdown on tumour behaviour, we first examined the effect of FBXO45 on cell growth in a proliferation and cytotoxicity assay." (PMID 36980776, 2023). "The unfavourable prognostic role in tumour diseases is attributed to the anti-apoptotic function of FBXO45, resulting from the various target proteins that predominantly act as tumour suppressors." (PMID 36980776, 2023). "Together, these indicated that silencing Fbxo45 played additive effects with Afatinib on suppressing the tumor growth of H1975 cells, even though harboring EGFR‐T790M resistance mutation and KRAS mutation, in vitro and in vivo." (PMID 35838331, 2022). "Tumor mass weights and volumes were markedly increased in Fbxo45-overexpressing compared with control mice." (PMID 35279684, 2022). "Among 60 cases with high expression of Fbxo45 in tumor tissues, 53 cases showed low USP49 expression (p = 0.0320)." (PMID 35279684, 2022). "Increasing evidence has shown that Fbxo45 functions as an oncogene to promote cancer cell survival, tumor growth, and chemotherapy resistance." (PMID 35838331, 2022). "From in vivo experiments, we observed that overexpression of Fbxo45 in Panc-1 cells promoted tumor growth in xenograft mouse models." (PMID 35279684, 2022). "To understand the effect of miR‐30e on modulation of ubiquitin proteosome pathway (UPS), we examined expression of FBXW7, a E3 ubiquitin ligase tumor suppressor and one of the targets of FBXO45." (PMID 35612714, 2022). "Consistent with that, the tumor cell proliferation and colony formation were also rescued by re‐applied Fbxo45." (PMID 35838331, 2022). "Recently, another study demonstrated that DNAJB9 blocked the tumor metastasis by enhancing Fbxo45-involved degradation of ZEB1 in TNBC cells." (PMID 35279684, 2022). "Xenograft mouse experiments demonstrated that ectopic expression of Fbxo45 enhanced tumor growth in mice and that USP49 overexpression inhibited tumor growth in vivo." (PMID 35279684, 2022). "The FBXO family F-box protein, FBXO45, has been previously recognized to play a role in neoplasia, nervous system and psychiatric disorders, and inflammatory disorders." (PMID 36379255, 2022). "Elevated protein levels of the ubiquitin E3 ligase adaptor FBXO45 promote tumor progression by stimulating ubiquitination of IGF2BP1 in hepatic cancer." (PMID 36293188, 2022). "In the subcutaneously xenografted nude mice, A549 cells with abrogated Fbxo45 were significantly attenuated for tumor growth compared with the control cells with ‘normal’ Fbxo45 expression." (PMID 35838331, 2022). "We found that Fbxo45 expression in tumor tissues was higher than the Fbxo45 expression in tumor-adjacent normal tissues and was associated with survival in PC samples (p = 0.0022)." (PMID 35279684, 2022). "IHC analysis on HCC samples showed that FBXO45 expression was positively associated with tumor size, tumor differentiation, and TNM stage, indicating that FBXO45 expression positively correlated with HCC disease progression." (PMID 34779401, 2021). "GSE62452 demonstrated that the higher expression levels of FBXO1, FBXO20, FBXO32, and FBXO45 were correlated with poorer tumor differentiation (N = 68), apart from FBXO22 and FBXO38." (PMID 35046938, 2021).
tumor (continued). "In this article, we describe the expression of FBXO45 in several types of human tumour specimens and highlight the downstream substrates of FBXO45." (PMID 32655893, 2020). "In the following paragraphs, we will describe the expression of FBXO45 in human tumour specimens and identify substrates of FBXO45 in cancer and its biological functions in the regulation of proliferation, apoptosis, cell cycle, motility and metastasis." (PMID 32655893, 2020). "Taken together, these data demonstrated that miR-27a* mediates tumor cell EMT processes through stabilizing the core EMT-TFs by direct suppression of Fbxo45 that is a module of SPF ubiquitin E3 complex." (PMID 25460509, 2015). "Instead, Fbxo45 molecule as a component of Skp1-Pam-Fbxo45 complex, namely SPFFbxo45, plays a part in the embryogenesis, synapse formation or apoptosis in tumor." (PMID 25460509, 2015). "In this study, we also demonstrate that miR-27a* directly targeted Fbxo45 thus enhancing the protein stabilities of EMT-TFs to promote tumor cell EMT processes by using P69 and M12 cell lines, which are an ideal pair of cell model for EMT study." (PMID 25460509, 2015). "FBXO45 has been identified to regulate oncogenesis and tumor progression in various cancer types." (PMID 38773471, 2024). "A recent study showed that FBXO45 is downregulated by the tumour-suppressive microRNA-30e." (PMID 36980776, 2023). "Likewise, the anchorage‐independent growth assay revealed the consistent outcomes that Fbxo45 promoted tumor growth in the soft agar." (PMID 35838331, 2022). "Importantly, USP49 partly rescued the Fbxo45-mediated promotion of cell growth and migration and invasion in PC cells, indicating that Fbxo45 performs its tumor promoter function via degradation of USP49 in PC cells." (PMID 35279684, 2022). "Together, these results revealed that Fbxo45 could substantively activate ERK to promote tumor development by suppressing the NP‐STEP46 in NSCLC cells." (PMID 35838331, 2022). "Fbxo45 silencing can significantly inhibit cell proliferation and tumor growth." (PMID 35838331, 2022). "Fbxo45 was recently identified to promote tumor initiation and progression, suggesting that the Fbxo45 oncoprotein might be a potential tumor therapeutic target." (PMID 35279684, 2022). "There is evidence that FBXO45 mediates ubiquitylation and proteasomal degradation of prostate apoptosis response protein 4, a tumor suppressor protein located in the cytoplasm, to develop a critical role in survival and activity of tumor cells." (PMID 33622332, 2021). "Accumulating evidence shows that FBXO45 has diverse roles in tumorigenesis and tumor progression." (PMID 33966034, 2021). "As for FBXO5, FBXO22, FBXO28, FBXO31 and FBXO45, they may be the independent poor prognostic factors of BC and the expression levels of which were closely related to different tumor stages." (PMID 33622332, 2021). "Consistently, RP11 decreased the expression of Siah1 and Fbxo45 in HCT-15 tumour xenografts." (PMID 30979372, 2019). "Notably, overexpression of FBXO45 facilitated tumor growth in mice." (PMID 38773471, 2024). "Another interesting target of FBXO45, FBXW7, is a tumour suppressor that targets specific substrates for ubiquitination and degradation, including the known driver oncogenes of aggressive PCA MYC and Mcl-1." (PMID 36980776, 2023). "In this work, we reported that Fbxo45 is overexpressed in NSCLC and is closely related to the overall survival of NSCLC patients and the capability to promote tumor cell growth in vitro and in vivo." (PMID 35838331, 2022). "UCSC Xena analysis of the TCGA PRAD dataset (n = 623) showed significant upregulation of FBXO45, SRSF7 and MYBL2 mRNAs in the PCa tumor tissues 50–60% compared to normal." (PMID 35612714, 2022). "Strikingly, data from The Cancer Genome Atlas (TCGA) database showed that the expression of FBXO45 was significantly correlated with AFP, tumor differentiation, tumor stage, and TNM stage." (PMID 34779401, 2021).
tumor (continued). "Moreover, this study identified that the miR-27a/Fbxo45/EMT-TF axis contributed to EMT development and tumor progression." (PMID 35279684, 2022). "In addition, the high Fbxo45 expression was distinctly alone with the high pERK level and the low NP‐STEP level and vice versa according to the H&E and IHC detection of the xenograft tumor samples from mice." (PMID 35838331, 2022). "Furthermore, FBXO45 modulated the process of EMT via mediating the ubiquitination and degradation of substantial EMT-related transcription factors, such as Twist1, Snai1/2, and Zeb1/2, in tumor cells." (PMID 35046938, 2021). "Finally, miR-27a*, as a potential onco-miR, can trigger tumor cell EMT initiation and promote cancer progression via directly targeting Fbxo45 to disrupt the SPFFbxo45 complex, thereby maintaining the protein stabilities of EMT-TFs, along with characteristic phenotypes of malignant cells." (PMID 25460509, 2015).
cancer (17 papers, 2015 to 2025). A tumor composed of atypical neoplastic, often pleomorphic cells that invade other tissues. "KEGG enrichment analysis of the high-expression group revealed a significant association of FBXO45 with cancer-related pathways, the cell cycle, RNA transport, and WNT signaling pathways." (PMID 40990020, 2025). "Our findings displayed that the FBXO45 protein levels were obviously attenuated in the TNBC cancer tissues in comparison with the associated adjoining normal tissues." (PMID 35802537, 2022). "Alternatively, the observations that JAK-STAT inhibitors are currently in use in the clinical setting as antitumor therapeutics suggest that FBXO45 activation might interact with other yet unknown clients to induce cell proliferation linked to JAK-STAT1 activation that impact development of cancer." (PMID 36379255, 2022). "FBXO45 is a E3 ubiquitin ligase that is overexpressed in many cancers, and high expression of FBXO45 is also correlated with poor survival in many cancers." (PMID 35612714, 2022). "FBXO45 targets the pro‐apoptotic Par‐4, first identified in prostate cells for proteosomal degradation resulting in increased survival of cancer cells." (PMID 35612714, 2022). "Several studies have reported the overexpression of FBXO45 in human cancer and an essential role for FBXO45 in tumorigenesis and progression." (PMID 33921128, 2021). "Another study validated that prostate apoptosis response protein 4 (Par-4), an anticancer protein that induces apoptosis, was a downstream substrate of FBXO45 in cancer cells." (PMID 32655893, 2020). "Consistently, data from TCGA show that high expression of FBXO45 is correlated with shortened overall survival in multiple types of human cancers." (PMID 32655893, 2020). "By screening for factors responsible for the stability of Zeb1 in cancer cells, we confirm that the downregulation of Siah1 and Fbxo45 mediates the RP11-induced stabilization of Zeb1 in CRC cells." (PMID 30979372, 2019). "Par-4 possesses various domain including the nuclear localization sequence (NLS1&2), the VASA domain for ubiquitination by Fbxo45, the selective for apoptosis in cancer cells domain (SAC) and a leucine zipper domain." (PMID 27175591, 2016). "On the other hand, FBXO45 has recently been implicated in the regulation of EMT and apoptosis in cancer cells." (PMID 26068074, 2015). "Recent studies indicate the prognostic potential of FBXO45 in several cancers." (PMID 36980776, 2023). "IGF2BP1 is a substrate of the E3 ligase adaptor FBXO45 and potential cancer therapeutic target." (PMID 36293188, 2022). "FBXO45 is a therapeutic target in cancer and IGF2BP1 may also be considered a potential therapeutic target in PF_EPN_A." (PMID 36293188, 2022). "Accumulating evidence has demonstrated that Fbxo45 exhibits a critical biological function in carcinogenesis and progression, indicating that targeting Fbxo45 may be a potential strategy for cancer therapy." (PMID 35279684, 2022). "As FBXO45 has a critical role in tumorigenesis and progression, FBXO45 might be a novel therapeutic target for cancer treatment." (PMID 32655893, 2020). "Lastly, we will update briefly about the role of FBXO45 in cancer." (PMID 32226545, 2020). "A study showed that miR-27a could inhibit the expression of FBXO45, leading to accumulation of the downstream substrates of FBXO45 and modulation of cancer initiation and progression, indicating that FBXO45 is a direct target of miR-27a30." (PMID 32655893, 2020). "Therefore, modulation of miR-27a, Hey1, m6A and RP11 could affect the FBXO45 expression level as a potential approach to treat cancer patients with high FBXO45 expression." (PMID 32655893, 2020). "FBXO45 also degrades prostate apoptosis response protein 4 (PAR4) to block selective cell death and promotes cancer cell proliferation and survival." (PMID 32226545, 2020). "Data from The Cancer Genome Atlas (TCGA) and GTEx, termed GEPIA, show that FBXO45 is highly expressed in a majority of human cancers." (PMID 32655893, 2020).
cancer (continued). "We also find that miR-27a* transcriptionally suppresses the expression of Fbxo45 to influence the formation of SPFFbxo45 complex, resulting in stabilization of EMT-TFs which contribute the EMT initiation and cancer progression." (PMID 25460509, 2015). "According to the Pan‐cancer analysis, Fbxo45 transcripts are significantly enhanced in tumors compared with normal tissues, except those cancer types with no standard control." (PMID 35838331, 2022). "Moreover, FBXO45 inhibited cancer development and metastasis by targeting EMT-inducing transcription factors, including SNAI1/2, TWIST1/2, and ZEB1/2, in various cancer cells." (PMID 33966034, 2021). "In conclusion, we propose that a novel signaling axis miR-27a*/Fbxo45/EMT-TFs may play a crucial role in EMT occurrence, cancer initiation and metastasis." (PMID 25460509, 2015). "Finally, our findings provide novel insight into the role of Fbxo45 in NSCLC and may offer an attractive therapeutic target and strategy for this cancer disease." (PMID 35838331, 2022). "Second, the knockdown of RBX1 remarkably raised the FBXO45 protein level, but the expression of FBXO45 mRNA was not affected in TNBC cancer cells with RBX1 knockdown." (PMID 35802537, 2022). "The bioinformatics results also showed higher expression of Fbxo45 and lower expression of USP49 in cancer tissues than in normal tissues." (PMID 35279684, 2022).
infection (1 paper, 2022). The state of being infected such as from the introduction of a foreign agent such as serum, vaccine, antigenic substance or organism. "Infection of BEAS-2B cells with various MOI of PR8 and FBXO45 silencing also led to a substantial increase in ISG expression, an effect not observed after IFNLR1 cellular depletion." (PMID 36379255, 2022). "Interestingly, FBXO45 silencing and subsequent PR8 infection reduced matrix 1/matrix 2 (M1/M2) proteins." (PMID 36379255, 2022).
nervous system diseases (1 paper, 2020). "FBXO protein 45 (FBXO45), a substrate-recognition subunit of E3 ligases, has been characterised to have pivotal roles in many human diseases, including nervous system diseases, inflammatory diseases and human malignancies." (PMID 32655893, 2020).
FBXO45 also shares sentences with these, for which no sentence is quoted: schizophrenia (3 papers); triple-negative breast carcinoma (2); diabetic nephropathy (1); Hypertension (1); microcephaly (1); mucinous carcinoma (1); neurodevelopmental disorder (1); psychiatric disorder (1); serous carcinoma (1); tuberous sclerosis (1).